CHRM2 (cholinergic receptor muscarinic 2)
Description:
Muscarinic receptor for acetylcholine, a neurotransmitter found in the brain, neuromuscular junctions and the autonomic ganglia. Ligand binding causes a conformation change that triggers signaling via guanine nucleotide-binding proteins (G proteins) and modulates the activity of downstream effectors, such as adenylate cyclase. CHRM2 is coupled to G(i)/G(o) (GNAI1 or GNAO1) G proteins and mediates signaling by inhibiting adenylate cyclase activity.
Synonyms: HM2
Tractability: Small molecule: an approved drug acts on it; a structure with a bound ligand is known; a high-quality ligand is known; it belongs to a druggable protein family. Antibody: UniProt places it where antibodies can reach, with high confidence; its Gene Ontology location is reachable by antibodies, with high confidence; UniProt predicts a signal peptide or a membrane-spanning region; the Human Protein Atlas places it where antibodies can reach. PROTAC: a small molecule that binds it is known.
Target class: Small molecule receptor (family A GPCR); Acetylcholine receptor; Monoamine receptor; Family A G protein-coupled receptor; Membrane receptor
Chemical probes: BATEFENTEROL
Safety:
Unwanted effects reported when the protein is acted on. In parentheses: how it was acted on, where the effect was seen, and who reports it.
bronchoconstriction (Bowes et al. (2012): inhibition, cardiovascular system; Lynch et al. (2017): inhibition, acute dosing, nervous system, respiratory, cardiovascular)
tachycardia (inhibition; cardiovascular system; sources: Bowes et al. (2012), Urban et al. (2012))
tremors (Bowes et al. (2012): inhibition, cardiovascular system; Lynch et al. (2017): inhibition, acute dosing, nervous system, respiratory, cardiovascular)
acidosis (activation, acute dosing; nervous system, respiratory, cardiovascular; source: Lynch et al. (2017))
blurred vision (activation, acute dosing; nervous system, respiratory, cardiovascular; source: Lynch et al. (2017))
bradycardia (activation; cardiovascular system; source: Urban et al. (2012))
bronchorrhea (activation, acute dosing; nervous system, respiratory, cardiovascular; source: Lynch et al. (2017))
bronchospasm (activation, acute dosing; nervous system, respiratory, cardiovascular; source: Lynch et al. (2017))
cough (activation, acute dosing; nervous system, respiratory, cardiovascular; source: Lynch et al. (2017))
decreased cardiac action potential duration (activation; cardiovascular system; source: Bowes et al. (2012))
decreased cardiac conduction (PR interval) (activation; cardiovascular system; source: Bowes et al. (2012))
decreased heart rate (activation; cardiovascular system; source: Bowes et al. (2012))
decreased PR interval (activation, acute dosing; nervous system, respiratory, cardiovascular; source: Lynch et al. (2017))
decreased pupil diameter (activation, acute dosing; nervous system, respiratory, cardiovascular; source: Lynch et al. (2017))
decreased/increased heart rate (activation, acute dosing; nervous system, respiratory, cardiovascular; source: Lynch et al. (2017))
decreased/increased respiratory rate (activation, acute dosing; nervous system, respiratory, cardiovascular; source: Lynch et al. (2017))
dysrhythmia (inhibition; cardiovascular system; source: Urban et al. (2012))
exhaustion (activation, acute dosing; nervous system, respiratory, cardiovascular; source: Lynch et al. (2017))
frothing (activation, acute dosing; nervous system, respiratory, cardiovascular; source: Lynch et al. (2017))
increased blood pressure (activation; cardiovascular system; source: Bowes et al. (2012))
increased body temperature (activation, acute dosing; nervous system, respiratory, cardiovascular; source: Lynch et al. (2017))
increased heart rate (inhibition, acute dosing; nervous system, respiratory, cardiovascular; source: Lynch et al. (2017))
increased salivation (activation, acute dosing; nervous system, respiratory, cardiovascular; source: Lynch et al. (2017))
increased/decreased blood pressure (activation, acute dosing; nervous system, respiratory, cardiovascular; source: Lynch et al. (2017))
irritability (activation, acute dosing; nervous system, respiratory, cardiovascular; source: Lynch et al. (2017))
lacrimation (activation, acute dosing; nervous system, respiratory, cardiovascular; source: Lynch et al. (2017))
muscle cramps (activation, acute dosing; nervous system, respiratory, cardiovascular; source: Lynch et al. (2017))
negative chronotropy and inotropy (activation; cardiovascular system; source: Bowes et al. (2012))
palpitations (inhibition; cardiovascular system; source: Urban et al. (2012))
peripheral edema (inhibition; cardiovascular system; source: Urban et al. (2012))
and 6 more effects
Gene: Protein-coding gene on chromosome 7 (136,868,652 to 137,020,255, forward strand). Ensembl gene ENSG00000181072.
Subcellular location: Cell membrane; Postsynaptic cell membrane
Pathways (Reactome):
Signal Transduction: G alpha (i) signalling events; Muscarinic acetylcholine receptors
Vesicle-mediated transport: Cargo recognition for clathrin-mediated endocytosis; Clathrin-mediated endocytosis
Gene Ontology:
Molecular function: arrestin family protein binding; G protein-coupled acetylcholine receptor activity; protein binding; G protein-coupled receptor activity
Biological process: adenylate cyclase-inhibiting G protein-coupled acetylcholine receptor signaling pathway; adenylate cyclase-inhibiting G protein-coupled receptor signaling pathway; G protein-coupled acetylcholine receptor signaling pathway; response to virus; adenylate cyclase-modulating G protein-coupled receptor signaling pathway; chemical synaptic transmission; G protein-coupled receptor signaling pathway; G protein-coupled receptor signaling pathway, coupled to cyclic nucleotide second messenger; nervous system development; phospholipase C-activating G protein-coupled acetylcholine receptor signaling pathway; regulation of heart contraction; regulation of smooth muscle contraction; presynaptic modulation of chemical synaptic transmission
Cellular component: membrane; plasma membrane; clathrin-coated endocytic vesicle membrane; dendrite; synapse; cholinergic synapse; postsynaptic membrane; presynapse
Genetic constraint (gnomAD): Loss-of-function variants: 8 observed, 26.03 expected, observed/expected ratio (o/e) 0.31, 90% interval 0.18 to 0.56. The upper end of that interval is the gene's LOEUF score, 0.56, which puts it in group 2 of 6, group 1 being the genes least tolerant of losing a copy. Missense variants: 440 observed, 595.83 expected, observed/expected ratio (o/e) 0.74, 90% interval 0.68 to 0.8. Synonymous variants: 202 observed, 218.56 expected, observed/expected ratio (o/e) 0.92, 90% interval 0.82 to 1.04.
Homologues: Orthologues: chimpanzee CHRM2 (100% identical), macaque CHRM2 (99% identical), dog CHRM2 (97% identical), pig CHRM2 (97% identical), rabbit CHRM2 (97% identical), mouse Chrm2 (96% identical), rat Chrm2 (96% identical), guinea pig CHRM2 (95% identical), tropical clawed frog chrm2 (82% identical), zebrafish chrm2a (72% identical), zebrafish chrm2b (57% identical). Paralogues in human: CHRM4 (59% identical), CHRM3 (47% identical), CHRM5 (42% identical), CHRM1 (41% identical), HRH1 (24% identical), HTR1A (23% identical), DRD5 (22% identical), DRD1 (21% identical), DRD3 (21% identical), HRH3 (21% identical), DRD4 (20% identical), HTR4 (20% identical), and 13 more.